TNF (tumor necrosis factor)
Diseases named in the same sentence as TNF in open-access papers (continued):
Sharing a sentence is not in itself a finding about the gene and the disease.
Sepsis (continued). "In sepsis, macrophages are overactivated and release a large number of pro-inflammatory cytokines, including IL-1β, IL-6, TNF-α, etc., leading to organ damage and death." (PMID 36743669, 2022). "In our study, TNF-α peaked at 6 h after sepsis, while another study showed a 24-h peak level of TNF-α." (PMID 35743025, 2022). "Our data showed that 12 h after the surgical procedure the animals had sepsis, since we observed bacterial growth in blood and increased serum concentrations of the inflammatory markers IL-6, TNF-α, KC, and MIP-2 in mice submitted to CLP compared to naïve." (PMID 35648977, 2022). "Compared with those in the sham group, the levels of IL-6, IL-1β and TNF-α in the sepsis group were increased (P < 0.05), the MDA content was increased, and the SOD and CAT activities were decreased (P < 0.05)." (PMID 35576220, 2022). "In a clinical trial, TNF-α blockade therapy in patients with sepsis significantly reduced mortality 3 days after infusion, and at 28 days following treatment, a trend toward reduced mortality continued, but the difference in mortality was not significant." (PMID 35488237, 2022). "IL-6, another proinflammatory cytokine, is also involved in the pathogenesis of sepsis and is considered to be a better predictor of sepsis than TNF-α." (PMID 34757596, 2022). "A sepsis admission diagnosis was over-represented in patients with a strongly reduced TNF-α production-capacity." (PMID 35877767, 2022). "Myocardial TNF-α was an autocrine contributor to myocardial dysfunction and cardiomyocyte death in ischemia-reperfusion injury, sepsis, and chronic heart failure." (PMID 35814241, 2022). "The overexpression of many proinflammatory cytokines, such as TNF-α, IL-1β, and IL-6, is closely related to severe sepsis." (PMID 35370629, 2022). "IL-10 showed positive correlations with the other six cytokines studied in patients with sepsis, and with IL-1β, TNF-α, IL-6, and IL-8 in patients with septic shock." (PMID 36536294, 2022). "The results in this also showed that EA at ST36 inhibited the production of TNF-α, IL-1β, and IL-6 and increased IL-10 production in septic mice, suggesting its therapeutic effect on sepsis." (PMID 35722155, 2022). "Compared with those in the sepsis group, the levels of IL-6, IL-1β and TNF-α were increased (P < 0.05), the MDA content was increased, while the SOD and CAT activities were decreased in the sepsis + BAY 87–2243 group (P < 0.05)." (PMID 35576220, 2022). "The exact dynamics of TNF-α during sepsis is still controversial, but there is some work suggesting TNF-α as an early, proinflammatory cytokine." (PMID 34986787, 2022). "Studies on sepsis showed that TNF-α induced expression of ICAM-1 in endothelial cells was partially attenuated by miR-223 transferred by PMPs." (PMID 35983051, 2022). "Taken together, CD40L–CD40 signaling pathway participates in the activation of EGCs during sepsis and affects the release of inflammatory factors TNF-α and IL-1β of EGCs, thereby affecting the intestinal barrier permeability." (PMID 36303116, 2022). "The production of TNF-α, IL-10, and IL-12 from PBMCs was significantly increased after LPS stimulation of PBMCs from both controls and patients with sepsis." (PMID 35723375, 2022). "Consistent with the fact that the upregulated production and release of cytokines and chemokines contribute to sepsis and organ dysfunction, such as TNF-α, IL-6, and IL-1β, are positively related to multiple organ dysfunction syndrome (MODS) and mortality." (PMID 35184141, 2022). "Proinflammatory cytokines, such as TNF-alpha, IL-1b, and IL-6, have diverse effects in the regulation of immune reactions and inflammation, secondary to sepsis, hence they were the ones determined in our study." (PMID 36551850, 2022). "Curcumin (50 and 200 mg/kg, i.p.)also protected against sepsis-induced acute lung injury in rat model by down-regulating the inflammatory cytokines TNF-α, IL-8, and macrophage migration inhibitory factor (MIF) levels." (PMID 36588685, 2022).
Sepsis (continued). "In mice, increased endogenous oxytocin levels early in the course of sepsis reduced innate immune cell activation by decreasing pro-inflammatory cytokines (such as interleukin-1 and tumor necrosis factor-alpha)." (PMID 35572539, 2022). "During the early stage of CLP-induced sepsis, the body activates inflammatory responses and secretes early pro-inflammatory mediators, such as TNF-α and IL-1β, to protect against infection." (PMID 35225146, 2022). "The expression level of TREM-1, TNF-α, and IL-6 in the sepsis model showed a consistent expression trend in sepsis patients." (PMID 36110326, 2022). "For example, in the MONARCHS trial, which tested the effects of an anti-TNF antibody in patients with sepsis, only patients with high baseline IL-6 levels—reflecting enhanced systemic inflammation—were included in the primary efficacy analysis." (PMID 36140361, 2022). "In particular, male mice show a similar cardiac phenotype after sepsis in the presence, or absence, of leucocyte TNFα shedding, which suggests that intra-cardiac inflammation is key." (PMID 35723764, 2022). "Our previous studies indicated that serum IL-6 and TNF-α levels were significantly decreased in patients with sepsis or secondary hemophagocytic lymphohistiocytosis/macrophage activation syndrome received CRRT." (PMID 36263056, 2022). "Bacteremia and subsequent endotoxemia directly stimulate the release of inflammatory cytokines, including TNF-α, IL-1β, IL-6, IL-12, and IL-18 in sepsis." (PMID 36120368, 2022). "It frequently results in inflammation, such as sepsis, with the primary cytokines secreted being IL-1β, IL-6, and TNF-α." (PMID 35698506, 2022). "We found that IL-6, IL-10 and TNF-α levels of the ZM241385-treated sepsis group were decreased in the blood and peritoneal cavity." (PMID 36148230, 2022). "In the pathological process of sepsis, TNF-α can induce the release of downstream inflammatory mediators to cause oxidative stress imbalance." (PMID 35265263, 2022). "There was a statistically significant difference in the relative mRNA levels of IL-6 and TNF-α in the lung tissue of the sepsis group vs the sham group (P<0.05)." (PMID 36685507, 2022). "Levels of IL-6 and TNF-α have been widely assessed in clinical samples under various sepsis conditions and were correlated to disease severity." (PMID 35167625, 2022). "Levels of TNF-α in lung tissues in control group, sepsis group, sepsis+SO2 group, and SO2 group were 41.1 ± 7.33 pg/mg, 48.5 ± 2.80 pg/mg, 45.0 ± 5.13 pg/mg, and 44.2 ± 4.30 pg/mg, respectively." (PMID 35265263, 2022). "Sepsis induced an overexpression of the inflammatory mediators TNF-α, (p < 0.001) IL-6, (p < 0.001), IL-1β (p < 0.001) and IL-10 (p < 0.01)." (PMID 35795581, 2022). "The levels of IL-1, TNF-, and IL-6 in the serum of rats in the sepsis group were significantly higher, and there was more myocardial tissue edema and myocardial fiber breakage." (PMID 35982998, 2022). "LPS administration in mice is a widely used animal model to study sepsis, which partially mimics some of the initial clinical features in humans, including the serum increases of pro-inflammatory cytokines, such as TNFα, IL-6 and IL-1b." (PMID 35887265, 2022). "Sepsis is a systemic inflammatory response syndrome, often accompanied by the release of a large number of inflammatory cytokines, such as TNF-α and IL-6, in the central and peripheral nervous systems." (PMID 35571246, 2022). "Ca2+ was found to be significantly associated with high levels of proinflammatory cytokines (e.g., TNF-α and IL-6) and procalcitonin in severe sepsis." (PMID 35711261, 2022). "This rationale was followed in a study in which a neutralising polyclonal anti-TNFα antibody fragment called AZD9773 was administered to patients with severe sepsis." (PMID 35634305, 2022). "Nevertheless, the protein levels of IL-6 and TNF-α reported in included human in vivo studies were still in the value ranges of clinical samples of patients with sepsis or septic shock." (PMID 35167625, 2022).
Sepsis (continued). "TNFα and ROS significantly increase preceding cardiac damage and dysfunction following trauma, sepsis, and myocardial ischemia." (PMID 36012574, 2022). "Higher TNFα protein levels (mean difference: 27 pg mL−1 (95% CI: 2–56) in peritoneal fluid after 18 h of polymicrobial sepsis were measured in wild-type, compared to iRHOM2−/− mice (p = 0.026)." (PMID 35723764, 2022). "When TNFα-dependent activation of NF-κB is inhibited in sepsis patients, it is conceivable that this is insufficient to abolish inflammatory activation, as e.g. LPS-dependent endothelial inflammatory activation will still be possible." (PMID 35634305, 2022). "further suggested that activation of the TGFBR2/Smad pathway was responsible for LPS-induced sepsis, resulting in increased levels of IL-2 and TNF-α and reduced overall survival of mice with sepsis." (PMID 35090386, 2022). "Our results underscore a critical role of Trdmt1 in regulating the levels of inflammatory cytokines, especially TNF‐α in the sepsis model." (PMID 35474613, 2022). "Immunohistochemical data revealed a significant (p < 0.05) increase in the hepatic expression of the inflammatory mediator TNF-α in the untreated sepsis group." (PMID 36120368, 2022). "Regarding the decrease in TNF-α, a study carried out in mice with sepsis induced by LPS also observed a higher survival rate and a significant reduction in the production of TNF-α in the group treated with the M. nigra leaves extract." (PMID 36432875, 2022). "The ability of monocytes to produce TNF-α is enhanced after immunostimulant therapy in patients with sepsis." (PMID 36209190, 2022). "TNF-α, IL-6, and IL-1β are involved in LPS-induced tissue damage and are regarded as major regulators of severe inflammatory diseases such as sepsis." (PMID 35038964, 2022). "In our study, we found elevated IL-6 and TNF-α levels in the brain tissues of rats subjected to sepsis." (PMID 35949300, 2022). "The EVs containing histones released by mouse-derived BMDM interact with TLR4, displaying pro-inflammatory effect, which can promote the production of TNF, IL-6 and IL-1β, thereby increasing the lethality of sepsis." (PMID 35463634, 2022). "In a mice model of lethal sepsis, quercetin significantly attenuated LPS-induced production of TNF-α and IL-1β in RAW264.7 macrophages, and also inhibited the LPS-stimulated phosphorylation of the inhibitors of κB kinase (IKKs), Akt, and JNK." (PMID 36588685, 2022). "Clinical samples of patients with sepsis can have highly elevated levels of TNF-α and IL-6 within one day of diagnosis." (PMID 35167625, 2022). "And TNF inhibits neutrophil migration to the peritoneum in response to polymicrobial sepsis by decreasing CXCR2 expression and inducing apoptosis." (PMID 35819838, 2022). "In the early stage of sepsis, M1 macrophages accumulate significantly, leading to the massive production of proinflammatory factors such as interleukin 1β (IL-1β), IL-6, tumor necrosis factor-α (TNF-α) and inducible nitric oxide synthase (iNOS)." (PMID 35603523, 2022). "HU-308 has been reported to reduce plasma CXCL1, CXCL2, and TNFα in rodent models of sepsis, hepatic injury, and nephropathy." (PMID 36555499, 2022). "CLP-induced sepsis significantly enhanced the TNF-α levels in the brain tissue samples in comparison with the sham group (P<0.01)." (PMID 35949300, 2022). "Immunohistochemistry and Western blotting analysis of liver tissue also revealed that the levels of IL-6 and TNF-α protein expression were considerably greater in the sepsis group." (PMID 36685507, 2022). "FTB, DNase1, FTB + DNase1, Cl-amidine, and FTB + Cl-amidine treatment lowered the levels of CRP, IL-6, IL-1β, and TNF-α in rats with sepsis." (PMID 36408247, 2022). "XBJI treatment reduces mortality, anal temperature, and the expression of inflammatory factors such as TNF-α, IL-1β, and IL-6 when administered to mouse sepsis models." (PMID 36361915, 2022).
Sepsis (continued). "These PD-1 knockouts also have increased production of cytokines following sepsis, specifically IL-6, IL-10, and TNF-α, as well as differences in the cell composition of peritoneal infiltrates." (PMID 35860251, 2022). "Pharmacological inhibition of mitoNEET using mitoNEET ligand-1 (NL-1) decreased the levels of pro-inflammatory cytokines such as IL-1β, IL-6, and TNF-α in animal models of sepsis, as well as LPS-induced inflammatory responses by macrophages in vitro." (PMID 35136051, 2022). "PCT has the advantage of maintaining high serum concentrations when compared to other sepsis markers such as tumour necrosis factor-alpha (TNF) and interleukin (IL)-6, making it more useful in the identification of sepsis." (PMID 35449688, 2022). "Rg4 also reduced the levels of TNF-α and IL-1β in the liver, which supported the anti-inflammatory activities of Rg4 on sepsis." (PMID 36142743, 2022). "Antimicrobials have an essential role in sepsis management and as an adjunct to anti-TNF drugs or thiopurines." (PMID 36284816, 2022). "In the initial stage of sepsis, increased inflammatory cytokines (TNF-α, IL-6, and IL-1β) lead to an inflammatory cytokine storm, which is a main cause of death in this stage." (PMID 35706715, 2022). "Wild–type mice exhibited rapid induction of TNF–α and IL–6 in the early stage of sepsis and a significant decrease in TNF–α and IL–6 levels thereafter and increased production of antiinflammatory IL–10 cytokine in the LPS model." (PMID 35911737, 2022). "At the same time, the use of resveratrol in the CLP sepsis rat model decreased the sepsis-induced cardiomyocyte apoptosis and reduced the inflammatory cytokine TNF-α in serum and IL-1β in myocardial tissues." (PMID 35222035, 2022). "NM administration significantly diminished the plasma levels of IL-1β, TNF-α, and IL-6 compared to the sepsis control." (PMID 35345558, 2022). "S1P lyase inhibition increases S1P, reduces cytokine production including TNF-α and IL-6 and protects against sepsis via the S1P-S1PR3 axis." (PMID 35094654, 2022). "The blood glucose level of patients with sepsis was positively correlated with the levels of IL-6, TNF-α, and IL-1β and was negatively correlated with the levels of CD4+/CD8+." (PMID 35664433, 2022). "Increases in the levels of TNF-α, IL-6 and IL-1β in the plasma indicated increased inflammation in the rats with sepsis." (PMID 35576220, 2022). "With its effects on escalating inflammation and activating the cell death processes of necroptosis, pyroptosis, and apoptosis, the major role of TNF-α in mediating sepsis-induced vital organ injury (e.g., the lungs) is established." (PMID 35337084, 2022). "EtOH feeding to C57BL/6 mice significantly diminished survival rates and lung PTX3 expression in a model of sepsis, and delayed tumor necrosis factor α (TNFα) level increases in plasma." (PMID 35634317, 2022). "ELISA showed that CLP-induced sepsis promoted the expression of inflammatory factors TNF-α, IL-1β, and IL-6." (PMID 35979014, 2022). "Our data suggested that the relative mRNA levels and protein levels of inflammatory factors (IL-6 and TNF-a) extracted from three organs—the lung, liver, and kidney—were considerably greater in the sepsis group than in the sham group." (PMID 36685507, 2022). "LPS-mediated sepsis significantly increased inflammatory cytokines than the control group, including TNF-α, IL-6, IL-10, MCP1, as well as ROS production, in the mouse heart." (PMID 35402535, 2022). "B cells can produce a large number of pro-inflammatory cytokines such as IL-3, IL-6, GM-CSF, and TNF-α to enhance the systemic inflammatory responses in sepsis." (PMID 36425582, 2022). "Our previous study indicated that CRRT significantly decreases serum levels of TNF-α and IL-6 in sepsis." (PMID 36263056, 2022). "In sepsis induced by bacterial pathogens, the inflammatory cytokines such as IL-1β, IL-6, and TNF-α function as major mediators for shock and death induction." (PMID 35892383, 2022).
Sepsis (continued). "The levels of IL-6, TNF-α, and IL-1β in the control group were the lowest, and those in the sepsis group were the highest." (PMID 35186224, 2022). "The results hinted that the continuous and unopposed inflammatory processes in sepsis encouraged TNF-α production along with corresponding catabolic effects against the murine skeletal muscle." (PMID 36016684, 2022). "We found that TNF-α, IL-6, and IL-1β were significantly increased in the sepsis group, offset by 3PO and Gsdmd gene deletion." (PMID 36589684, 2022). "MFA, especially at the highest dose, reduced cytokine levels (IL-1β, IL-18, and TNF-α) in the early stages of sepsis, favoring a balance of the immune system and of equilibrium of inflammatory components, crucial for the development of a favorable outcome." (PMID 36333747, 2022). "In sepsis, monocytes activated by proinflammatory cytokines (TNF-alpha, IL-1beta) will express tissue factor (TF) on their surface." (PMID 36289881, 2022). "During the stage of sepsis-induced immunosuppression, the release of TNF-α by monocytes is significantly reduced." (PMID 36209190, 2022). "But similar concentration of TNF-α and IL-6 was observed between WT-sepsis and Card9−/−-sepsis mice." (PMID 35618701, 2022). "IL-6 and TNF-α levels of mice at ST and IT after in vivo challenge were generally comparable to serum and plasma levels of humans with sepsis or septic shock." (PMID 35167625, 2022). "Specifically, evoked supernatant concentrations of TNF, IL-6, IL-1α, IL-1β, and IL-8 were all substantially less in assays of sepsis patients’ samples, despite greater baseline concentrations and ongoing inflammatory activity when compared to controls." (PMID 35981050, 2022). "A blunted TNF-α response in sTBI to LPS stimulation has been previously demonstrated in sepsis and trauma in children." (PMID 35130911, 2022). "Hypernatremia on admission is associated with increased hospital mortality and abnormal immune response in sepsis, as demonstrated by the downregulation of G-CSF and TNF-α release after LPS stimulation of cells ex vivo." (PMID 36140385, 2022). "In sepsis, the inflammatory cytokines include tumor necrosis factor-α (TNF-α), interleukin-18 (IL-18), and interleukin-1β (IL-1β)." (PMID 36199375, 2022). "The mean concentration of proximal proinflammatory mediator TNF-alpha was 5 pg/mL in COVID-19 patients, 34.6 pg/mL in patients with sepsis and 52.2 pg/mL in patients with CRS." (PMID 36289881, 2022). "In sepsis, TNF-α is released by the impairment of endothelial cell barrier function, resulting in abnormal vascular function." (PMID 35246004, 2022). "Immunohistochemical (IHC) analysis of paraffin-embedded lungs illustrated that the levels of IL-6 and TNF-α were considerably greater in the sepsis group than in the sham group." (PMID 36685507, 2022). "Skin lesions resolved gradually after anti-TNF-α biologics rescue; tacrolimus and corticosteroid therapy were re-administrated after controlling sepsis." (PMID 36059444, 2022). "The results indicated that the compounds played anti-sepsis effect through inhibiting the release of NO, IL-1β, IL-6, and TNF-α mediated by LPS and regulating the LPS-TLR4/MD-2-NF-κB pathway by hydrophobic binding to the key protein MD-2." (PMID 36160407, 2022). "Some treatments for sepsis have focused on the neutralization of one or more inflammatory mediators, such as IL-1 receptor antagonists and anti-TNF-α antibodies." (PMID 35625251, 2022). "We found LPS-related sepsis visibly upregulated the mRNA expression of IL-6, TNF-α, pyrocytosis-related factors (such as caspase-1), hypoxia-inducible factors (such as HIF1-α), and chemokines." (PMID 35156512, 2022). "Pro-inflammatory cytokines and inflammatory biomarkers, such as C-reactive protein (CRP), IL-1, IL-6 and TNF-α, increase after the development of sepsis." (PMID 35193654, 2022).